CDC25A (cell division cycle 25A)
Diseases named in the same sentence as CDC25A in open-access papers (continued):
Sharing a sentence is not in itself a finding about the gene and the disease.
preeclampsia (1 paper, 2025). Preeclampsia is a hypertensive disorder of pregnancy that is characterized by new-onset hypertension with proteinuria presenting after 20 weeks of gestation, and depending on mild or severe forms may initially present with severe headache, visual disturbances, and hyperreflexia. "Ultimately, functional studies in relevant cell and animal models are essential to confirm the causal impact of ATG16L1, PMVK, MAP3K14, NSUN2, and CDC25A on senescence phenotypes and preeclampsia pathogenesis." (PMID 41220585, 2025). "CDC25A regulates cell cycle transitions, and its dysregulation is linked to senescence; a previous MR study also hinted at its involvement in preeclampsia." (PMID 41220585, 2025). "Key genes (ATG16L1, PMVK, MAP3K14, NSUN2, CDC25A) link cellular senescence to preeclampsia, offering insights for mechanistic studies and therapeutic targeting." (PMID 41220585, 2025). "Placental RT-PCR showed upregulated ATG16L1 and downregulated PMVK, MAP3K14, NSUN2, and CDC25A in preeclampsia." (PMID 41220585, 2025). "Using uterine eQTL data as a proxy for maternal contributions, we found that higher genetically predicted expression of CDC25A and NSUN2 was associated with decreased odds of preeclampsia." (PMID 41220585, 2025). "In conclusion, this multi-omics MR study, combined with preliminary experimental insights, pinpoints ATG16L1, PMVK, MAP3K14, NSUN2, and CDC25A as key candidate genes potentially mediating the link between cellular senescence pathways and odds of preeclampsia." (PMID 41220585, 2025). "These preliminary experimental findings lend support to the potential relevance of ATG16L1, PMVK, MAP3K14, NSUN2, and CDC25A dysregulation in preeclampsia pathophysiology." (PMID 41220585, 2025). "Our findings implicate several genes operating through diverse pathways—including ATG16L1, MAP3K14, PMVK, CDC25A, and NSUN2—as potential mediators linking senescence processes to odds of preeclampsia." (PMID 41220585, 2025). "Synthesizing these results, dysregulation across interconnected pathways—autophagy (ATG16L1), inflammation (MAP3K14), metabolism (PMVK), cell cycle (CDC25A), and RNA methylation (NSUN2)—appears to converge on promoting placental cellular senescence, contributing to preeclampsia pathophysiology." (PMID 41220585, 2025). "The results revealed that the expressions of ATG16L1, NSUN2 and PMVK were significantly downregulated in placental tissues from preeclampsia patients, whereas other key genes such as CDC25A and MAP3K14 did not vary significantly between groups." (PMID 41220585, 2025). "Collectively, these findings suggest that disruptions in placental cell cycle control (CDC25A) and RNA modification pathways (NSUN2) may contribute significantly to preeclampsia pathology." (PMID 41220585, 2025).
serous ovarian cancer (1 paper, 2020). "Cdc25A has also been shown to be overexpressed in other cancer types, including high-grade serous ovarian cancer and head-and-neck squamous cell carcinoma, which are characterized by genomic instability." (PMID 32964114, 2020).
small lung cell carcinoma (1 paper, 2020). "MiR-184 can inhibit cell proliferation and invasiveness via targeting CDC25A in small lung cell carcinoma." (PMID 32766356, 2020).
soft tissue sarcoma (1 paper, 2021). A malignant neoplasm arising from muscle tissue, adipose tissue, blood vessels, fibrous tissue, or other supportive tissues excluding the bones. "Downregulation of CCND1 and CDC25A genes was also observed in soft tissue sarcoma cell lines." (PMID 33923996, 2021).
teratocarcinoma (1 paper, 2025). A germ cell tumor characterized by the presence of an embryonal carcinoma component and a teratoma component. "Additionally, we observed the isoform switch of CDC25A from the full‐length isoform CDC25A‐1 (transcript ID: NM_001789.3) to the truncated isoform CDC25A‐2 (transcript ID: NM_201567.2), a reported alternative splicing event in teratocarcinoma not previously studied in the context of GBM39." (PMID 39974663, 2025).
thyroid tumours (1 paper, 2002). "Thus, we can hypothesise that cdc25A may be linked to the activation of cdks, making complexes with cyclins, although it is unlikely that both cdc25A and cdk-G1 cyclin complex are directly related to the cell proliferating activity of thyroid neoplasms." (PMID 12085185, 2002). "Cdc25A overexpression was observed in high incidences in all types of thyroid neoplasms." (PMID 12085185, 2002). "In summary, this study demonstrated that cdc25B and cdc25A may play an oncogenic role in thyroid neoplasms but may not be directly linked to the cell proliferation of thyroid tumours." (PMID 12085185, 2002).
viral infection (1 paper, 2022). "Furthermore, in viral infection, a study performing Sendai virus-infected cell line showed that upregulated CDC25A suppressed IFN-β activation while knockdown of CDC25A increased IFN-β stimulation." (PMID 35887528, 2022).
vulvar carcinoma (1 paper, 2010). "However, in our study overexpression of CDC25A was found not only in 51% of the vulvar carcinomas, but also in normal vulvar squamous epithelium, indicating that high expression of CDC25A is not important in the pathogenesis of vulvar carcinomas." (PMID 20500813, 2010). "High nuclear CDC25A and CDC25B expression were observed in 51% and 16% of the vulvar carcinomas, respectively, whereas high cytoplasmic CDC25C expression was seen in 63% of the cases." (PMID 20500813, 2010). "Expression of CDC25A, CDC25B, CDC25C and phosphorylated (phospho)-CDC25C (Ser216) were examined in 300 vulvar carcinomas using immunohistochemistry." (PMID 20500813, 2010). "In the present study, overexpression of CDC25A, CDC25B and CDC25C isoforms was not significant associated with each other, suggesting that overexpression of multiple isoforms in vulvar carcinomas occur through independent pathways." (PMID 20500813, 2010). "However, high phospho-CDC25C (Ser 216) expression was correlated with low expression of CDC25A and high expression of CDC25B, suggesting that the three can collaborate in the tumorigenesis of a subset of vulvar carcinomas." (PMID 20500813, 2010).
cancer (144 papers, 2001 to 2025). A tumor composed of atypical neoplastic, often pleomorphic cells that invade other tissues. "Overexpression of CDC25A is commonly observed in various cancers and is frequently linked to poor prognosis and resistance mechanisms through its regulation of the cell cycle and apoptosis." (PMID 40362252, 2025). "CDC25A plays a role in tumor initiation and progression and is associated with poor prognosis, making it a potential target for cancer therapy." (PMID 41373559, 2025). "CDC25A is considered an oncogene, as its overexpression correlates with tumoral development in many cancer types and is associated with alterations in relevant oncogenic pathways." (PMID 34363019, 2022). "CDC25A drives tumorigenesis of certain cancers, but the cell cycle ability of its splicing variants remains undocumented." (PMID 36539837, 2022). "CDC25A is worthy of attention because its overexpression in cancer has frequently been associated with genetic instability and checkpoint abrogation, contributing to malignancy and a poor prognosis." (PMID 36539837, 2022). "The Cdc25A protein is expressed highly in a variety of human cancer types and is frequently associated with high-grade tumors and confers poor prognosis." (PMID 34071237, 2021). "Emerging evidence suggests that the expression of CDC25A is elevated in a number of human cancers and is often associated with high grade tumors and a poor prognosis." (PMID 32127943, 2020). "Overexpression of CDC25A is known to be associated with malignancy and poor prognosis in cancer patients." (PMID 31540229, 2019). "High expression levels of CDK2, SKP2 and CDC25A are detected in several types of cancer, BC included, and implicated in the promotion of cancer cell proliferation." (PMID 31107884, 2019). "Highlighting the key role of CDC25A in tumorigenesis, it is frequently overexpressed in cancer cells and associated with poor cancer patient outcomes." (PMID 31779191, 2019). "Higher CDC25A expression has been reported in breast and other carcinoma and is associated with poor prognosis." (PMID 29416040, 2018). "Some of them have been reported to be cancer-associated genes such as CDC25A, CDKN1A, MMP1, MMP13 and SOX4." (PMID 27863388, 2016). "The over-expression of CDC25A was also associated with aggressive cancer phenotypes including portal vein invasion and dedifferentiated histology." (PMID 18269767, 2008). "Furthermore, CDC25A upregulation has been consistently associated with unfavorable prognoses across various cancer types." (PMID 39390252, 2024). "Moreover, CDC25A-mediated cell cycle progression has also been associated with chemo-resistance of cancer cells." (PMID 34266408, 2021). "Inhibition of Cdc25A degradation in turn should lead to its accumulation, accompanied by bypass of DNA damage and replication checkpoints, enhanced DNA damage and increased risk of cancer." (PMID 21310058, 2011). "Numerous studies demonstrated that CDC25A influenced cell mitosis, proliferation as well as the development and poor prognosis of malignant tumours." (PMID 40548841, 2025). "The expression of CDC25A was compared between various cancer cell lines and tissues and normal tissues using BioGPS (Supplementary S3)." (PMID 41373559, 2025). "In recent years, CDC25A has garnered exceptional interest due to its identified overexpression in various cancer types." (PMID 41373559, 2025). "It is indicated that abnormal expression levels of CDC25A can lead to cell cycle disruption, compromising DNA integrity and, as a result, the proliferation of malignant tumor cells." (PMID 40076252, 2025). "A key mechanism underlying the pro-meiotic effect of SMYD3 inhibition is the significant upregulation of CDC25A, a phosphatase recently shown in cancer cell models to be negatively regulated by SMYD3 through post-translational mechanisms." (PMID 40636673, 2025).
cancer (continued). "The opposite prognostic roles of miR‐195‐5p expression compared to CHEK1 and CDC25A gene expression in luminal BC patients suggested the functional relevance of this miRNA for CHEK1 and CDC25A in this cancer subtype." (PMID 40548926, 2025). "Numerous studies have demonstrated that the inhibition of CDC25A can enhance the sensitivity of cancer cells to radiation, impede the survival of cancer cell colonies, and facilitate apoptosis." (PMID 41373559, 2025). "Clinically, up-regulated IGF2BP3, METTL3, and CDC25A show a strong positive correlation in TCGA pan-cancer, including AEG." (PMID 39247830, 2024). "IHC results showed that METTL3, IGF2BP3, and CDC25A expression significantly increased in cancer tissues compared to normal adjacent tissues." (PMID 39247830, 2024). "It appears that ZBSO inhibits cancer through the downregulation of PCNA protein and pathways associated with CDC25A/CyclinB1/CDK1." (PMID 37081962, 2023). "Overexpression of CDC25A has been reported in multiple cancers such as HCC, and highly expressed CDC25A showed signs of poor prognosis." (PMID 36539837, 2022). "A depletion in USP47 decreases cell survival by inducing the accumulation of Cdc25A, and has anti-cancer effects on several cancer cell lines." (PMID 35205710, 2022). "First, Cdc25a is overexpressed in a wide variety of cancers and has a crucial role in cell proliferation and apoptosis and, when overexpressed, promotes tumorigenesis." (PMID 35572197, 2022). "Stratifying patients according to the combined expression of CCNE1 and CDC25A revealed the expected pattern across most types of cancer: TTLL11 is downregulated in tumors with high expression of at least one of the two potential TTLL11 upstream regulators." (PMID 36414642, 2022). "CDC25A is overexpressed in cancer and promotes tumorigenesis; interestingly, a genome-wide CRISPR screen showed that the absence of CDC25A leads to ATR inhibitor resistance." (PMID 36499000, 2022). "The high CDC25A expression has been found in different cancer types, and overexpression of CDC25A presents in approximately 50% of BC cases and implicates poor prognosis." (PMID 35036112, 2022). "In contrast, CDC25A is considered an oncogene since it is highly overexpressed in most cancer tissues, where proliferation is increased, leading to genomic instability." (PMID 34363019, 2022). "The function of miR-122 and its associated mRNAs such as TRIM29, Bcl-W, CCNG1, CDC25A, XIAP, and ALDOA are reportedly downregulated during cancer cell progression." (PMID 36499586, 2022). "mmp1 promotes cell cycle acceleration in cancer cells by activating the cdc25a/CDK4-cyclin D1 and p21/cdc2-cyclin B1 complexes." (PMID 36225568, 2022). "Silencing CDC25A or treating with CDC25A inhibitors can reverse B7-H3-induced cancer cell resistance." (PMID 34203270, 2021). "The CDC25A expression in cancer and normal tissues was predicted in the GEPIA database and that in CSCC and normal cells was determined by RT-qPCR and western blot assays." (PMID 34266408, 2021). "We also showed that USP29 played a critical role in Cdc25A-mediated regulation of the cell cycle in cancer cell lines and in tumor progression." (PMID 34071237, 2021). "Cell division cycle 25A (CDC25A) is a well-recognized regulator of cell cycle progression and is involved in cancer development." (PMID 34266408, 2021). "We also showed that USP29 knockdown hampered Cdc25A-mediated cell proliferation, migration, and invasion of cancer cells in vitro." (PMID 34071237, 2021). "For instance, tissue microarrays identified that LIN28A expression was increased in epithelial tumors and promoted cell cycle progression by regulating CDK2, CCND1, and CDC25A in cancer cells." (PMID 34868981, 2021).
cancer (continued). "In this study, we showed that ubiquitin-specific protease 29 (USP29) stabilized Cdc25A protein expression in cancer cell lines by protecting it from ubiquitin-mediated proteasomal degradation." (PMID 34071237, 2021). "Overexpression of Cdc25A in cancer cells reversed these changes, while knockdown of ErbB2 blocked the effects of Cdc25A overexpression." (PMID 34743185, 2021). "In cancer cells, the rate of Cdc25A protein turnover is controlled by the ubiquitin proteasomal pathway." (PMID 34071237, 2021). "By performing the MTT assay, we found that overexpression of Cdc25A recovered the viability of cancer cells treated with sorafenib." (PMID 34743185, 2021). "Meanwhile, the inhibition of FOXM1 repressed the expression of CDK6, CCND1, CDK2, CCNE2, E2F2, and CDC25A to arrest the cell cycle at G2 phase, which blocks the promotion of cancer-cell mitosis." (PMID 34880209, 2021). "In this subtype, FOXM1, TOP2A, CCNB1, CCNB2, and CDC25A participate in DNA repair and are activated during disease relapse or play a role in the prognosis of other cancers, thereby supporting the poor prognostic characteristics of the DP.BCG+ subtype." (PMID 33535616, 2021). "Overexpression of Cdc25A significantly increased ErbB2 mRNA and protein levels in cancer cells, while sorafenib treatment or PKM2-S37D overexpression reduced these levels." (PMID 34743185, 2021). "Cell division cycle 25A (Cdc25A) is a dual-specificity phosphatase that is overexpressed in several cancer cells and promotes tumorigenesis." (PMID 34071237, 2021). "CDC25A has a role in apoptosis/metastasis regulator; CDC25A overexpression increases tumorigenesis, and is often observed in various types of cancer." (PMID 33925358, 2021). "Previously, Dub3 was reported to be the deubiquitinating enzyme for Cdc25A as it acts to regulate the cancer cell cycle and tumor progression." (PMID 34071237, 2021). "It was found that CDC25A was highly expressed in the cancer tissues and positively correlated with the tumor staging." (PMID 34266408, 2021). "As an oncogenic protein, CDC25A is overexpressed in many types of cancer and correlates with poor prognosis." (PMID 32764536, 2020). "It has been identified as an oncogene and the overexpression of CDC25A is closely related to the occurrence of various cancers." (PMID 32766313, 2020). "CDC25A and B expression has been shown to be stimulated by the c-MYC oncogene and has been reported in many types of human cancers, possibly resulting from genome instability caused by the checkpoint-abrogating effect of their overexpression." (PMID 33385163, 2020). "Altogether, the results of our study indicate that MTA commits RCM‐1 cancer cells toward their differentiation into dome tissue via the down‐regulation and dysfunction of CDC25A and possibly of CCNE2, the key cell‐cycle regulators in the G1 phase." (PMID 33048473, 2020). "To target the interaction of 14-3-3ε with CDC25A for cancer therapy, we developed two novel phospho-peptides, pS and pT, corresponding to each of the 14-3-3 binding sites of CDC25A, to specifically interfere with 14-3-3ε binding to CDC25A." (PMID 32934772, 2020). "In this study, we demonstrated that compared with that of adjacent tissues, the positive rate of highly expressed CDC25A in cancer tissues was significantly higher, whereas miR‐122‐5p was significantly lowly expressed." (PMID 31505105, 2019). "This prediction correlates with biological knowledge about CDC25A inhibitors as potential anti-cancer agents." (PMID 29515890, 2018). "For example, in the bladder tumorigenesis case study, kali returned therapeutic bullets inhibiting the PI3K/Akt pathway or the CDC25A tyrosine phosphatase, two documented targets in cancer therapies." (PMID 29515890, 2018). "As overexpression of Cdc25A predicts the malignancy and poor prognosis in cancer patients, Cdc25A has emerged as a new target for cancer therapy." (PMID 29725502, 2018).